RYR1 (ryanodine receptor 1)
Diseases named in the same sentence as RYR1 in open-access papers (continued):
Sharing a sentence is not in itself a finding about the gene and the disease.
congenital myopathies (104 papers, 2007 to 2026). "Mutations in RyR1 linked to severe RYR1‐congenital myopathies affect calcium release from both extrafusal as well as intrafusal muscles." (PMID 41091627, 2025). "RYR1 mutations are commonly associated with congenital myopathies and can present with neuromuscular symptoms such as muscle weakness and paralysis." (PMID 41180248, 2025). "Such a (secondary) adaptative and detrimental role of aberrant post‐translational modifications on contractile proteins has already been demonstrated in the context of other congenital myopathies related to RYR1 mutations." (PMID 40320982, 2025). "Central Core Disease (CCD) is the most frequent congenital myopathy and, in approximately 90% of cases, is caused by RYR1 mutations." (PMID 41373610, 2025). "Nine congenital myopathy-associated genes were involved in the cases, with RYR1 being the most frequent." (PMID 40936319, 2025). "Pathogenic variants in RYR1 cause a spectrum of rare congenital myopathies associated with intracellular calcium dysregulation." (PMID 40846977, 2025). "High-risk patients include those with congenital myopathies (central core disease), confirmed or suspected RYR1 mutations, or prior intraoperative complications suggestive of MH." (PMID 40590017, 2025). "In the congenital myopathy subgroup, 12 of 22 patients (54.5%) had disease-causing variants in RYR1 (n = 4), MYH7 (n = 3), TTN (n = 2), FHL1 (n = 1), NEB (n = 1), and SELENON (n = 1)." (PMID 40494860, 2025). "Central Core Disease (CCD) is a congenital myopathy predominantly caused by mutations in the gene encoding ryanodine receptor type-1 (RYR1), the intracellular Ca2+ release channel embedded in the skeletal muscle sarcoplasmic reticulum membrane." (PMID 41373610, 2025). "RYR1, the gene encoding the calcium release channel of the sarcoplasmic reticulum, is the most common target of mutations linked to human congenital myopathies, a condition often accompanied by skeleton alterations and joint contractures." (PMID 41091627, 2025). "RYR1 variants account for a large proportion of cases with congenital myopathy, however, there is a very high degree of both clinical and genetic heterogeneity." (PMID 39409197, 2024). "In cohort studies, RYR1 variations account for 33 to 59% of patients with congenital myopathies, thus constituting one of the most frequent causes within this group of disorders." (PMID 39409197, 2024). "We present here a 6-year-old German patient with a severe congenital myopathy who was known to carry one pathogenic, maternally inherited, and presumably recessive RYR1 variant since his first year of life." (PMID 39409197, 2024). "In conclusion, we describe a second patient in whom WGS led to the definitive diagnosis of an RYR1-related congenital myopathy due to a deep intronic splice variant in this gene." (PMID 39409197, 2024). "Because of the pathogenic variants in the RYR1 gene implicated in various congenital myopathies, we review clinical concerns associated with LGMD and describe the anesthetic management of our patient with LGMD and a potentially difficult airway." (PMID 39385877, 2024). "Through whole genome sequencing we identified a second, deep intronic RYR1 variant that has recently been described in another patient with severe congenital myopathy and shown to affect splicing." (PMID 39409197, 2024). "We here describe a patient with a severe congenital myopathy who was known to carry one recessive pathogenic variant in RYR1 from the first year of life." (PMID 39409197, 2024). "We underline the suggestion that two hypomorphic RYR1 variants, in this case two splice variants, seem to be associated with a more severe disease course and severe congenital myopathy." (PMID 39409197, 2024). "We present a 6-year-old patient with severe congenital myopathy, carrying a heterozygous pathogenic RYR1 variant inherited from the healthy mother." (PMID 39409197, 2024).
congenital myopathies (continued). "Mutations in the gene RYR1 are also associated with three congenital myopathies and an isolated case of congenital myopathy characterized on histology by cores and rods." (PMID 37373564, 2023). "EOMs are also specifically spared in patients with Duchenne Muscular Dystrophy yet they are affected in patients with some congenital myopathies, including patients with recessive RYR1 myopathies carrying a hypomorphic or null allele." (PMID 36862731, 2023). "Conditions related to mutations in the gene encoding the skeletal muscle ryanodine receptor 1 (RYR1) are genetic muscle disorders and include congenital myopathies with permanent weakness, as well as episodic phenotypes such as rhabdomyolysis/myalgia." (PMID 37602753, 2023). "Mutations in the RyR1 gene manifest clinically in congenital myopathies and/or malignant hyperthermia susceptibility." (PMID 38136118, 2023). "There has been a recent explosion in the identification of new cases of congenital myopathies due to RYR1 mutations." (PMID 36833224, 2023). "Mutations in RyR1 cause a rare form of congenital myopathies collectively known as RyR1-related myopathies (RyR1-RM)." (PMID 36647824, 2023). "Since ophthalmoplegia is a common clinical sign observed in patients affect by congenital myopathies linked to recessive RYR1 mutations, we also investigated the proteome of EOMs from dHT and WT mice." (PMID 36862731, 2023). "Other congenital myopathies, including Duchenne muscular dystrophy and limb-girdle muscular dystrophy (β-sarcoglycan deficiency), have also been linked to RyR1 dysfunction and Ca2+ release." (PMID 36647824, 2023). "Congenital myopathies are a group of muscle diseases leading to a weak muscle phenotype caused by mutations in a number of genes including RYR1." (PMID 36862731, 2023). "Ryanodine receptor 1 (RYR1) gene-related pathogenic variations are the most frequent causes of congenital myopathies." (PMID 37627391, 2023). "Mutations in the SEPN1 gene, causing the knockdown of SELENON accompanied by recessive gene RYR1 that encodes ryanodine receptor 1 (RyR1), which are both proteins implicated in calcium homeostasis, cause severe congenital myopathies." (PMID 37958974, 2023). "A previous investigation in a larger group of 504 subjects found RYR1 to be the most frequently altered gene (24.3%) among those associated with congenital myopathies." (PMID 36833224, 2023). "As a major Ca2+ release channel of endoplasmic reticulum (ER), ryanodine receptor 1 (RyR1) key mutations are main causes of severe congenital myopathies." (PMID 35144690, 2022). "Patients with congenital myopathies such as MmD carrying recessive RYR1 mutations belonging to class 4 channel defects, typically exhibit non-progressive proximal muscle weakness." (PMID 35238775, 2022). "As of 2011, the prevalence of congenital myopathies due to RYR1 mutations is reported to be 1:90,000 in the United States." (PMID 35698232, 2022). "This study provides proof of concept for the pharmacological treatment of patients with congenital myopathies linked to recessive RYR1 mutations." (PMID 35238775, 2022). "Congenital myopathies are rare neuromuscular disorders, caused in approximately 30% of the patients, by mutations in the RYR1 gene." (PMID 35238775, 2022). "Next generation sequencing has resulted in an explosion in the identification of rare novel variants of RYR1, considering the large size of the RYR1 gene, and the frequency of RYR1 variations in congenital myopathy." (PMID 35693006, 2022). "Variations in the ryanodine receptor 1 gene (RYR1, MIM#180901), encoding the type 1 ryanodine receptor (RyR1), have been recognized as the most common cause of congenital myopathies." (PMID 35693006, 2022). "Diagnostic gene-sequencing has been employed to avoid RyR1-related congenital myopathies, and several disease-modulating therapeutic strategies and salvage therapies have been developed against RyR1-related myopathies." (PMID 35144690, 2022).
congenital myopathies (continued). "We are confident that this study provides proof of concept for a therapeutic strategy aimed to enhance muscle strength in patients affected by congenital myopathies linked to recessive RYR1 mutations." (PMID 35238775, 2022). "Pathogenic variants in the ryanodine receptor (RYR1) gene are the most common causes of congenital myopathy, and the most frequent cause of Central Core Disease." (PMID 35627144, 2022). "This study provides proof of concept for the treatment of patients with congenital myopathies linked to recessive RYR1 mutations, with small molecules inhibiting DNMT and histone deacetylases." (PMID 35238775, 2022). "RYR1 mutations can cause skeletal muscle dysfunction in children and adults, resulting in a wide range of disabilities, and are the most common cause of congenital myopathy." (PMID 34809703, 2021). "Autosomal dominant mutations in RYR1 have been associated with the core myopathies (CM), the most frequent congenital myopathy subtype." (PMID 34208776, 2021). "This database contains an RyR1 mutation at T4980M (rabbit RyR1 T4979M) associated with congenital myopathy." (PMID 34809703, 2021). "Mutations in RYR1 were associated with the specific subtypes of congenital myopathy, such as congenital fiber-type disproportion and rod-core myopathy." (PMID 34208776, 2021). "Here we report the identification of a recurrent RYR1 missense mutation in thirteen patients from nine unrelated families with atypical congenital myopathy associated with a benign disease course." (PMID 34535181, 2021). "The few available reports suggest some overlap with the milder end of the RYR1-associated congenital myopathy spectrum, or even a normal muscle biopsy appearance." (PMID 30788618, 2019). "We have delineated the key histopathological features, also in comparison to the already recognized RYR1-associated congenital myopathy spectrum, and have tried to establish tentative genotype–phenotype correlations on the histopathological level." (PMID 30788618, 2019). "Abnormalities on oxidative staining, generally considered to be more specifically associated with RYR1-related congenital myopathies, were observed in 52%, and included unevenness (n = 24), central cores (n = 7) and multi-minicores (n = 3)." (PMID 30788618, 2019). "In a previous study, A homozygous RYR1 mutation (c.8816G > A p.Arg2939Lys) in skeletal muscle was responsible for a 35-year-old male with congenital myopathy as well as a typical periodic paralysis." (PMID 31068157, 2019). "Although supraventricular arrhythmia is sometimes encountered in congenital myopathies, this is the first report of cardiac arrhythmia requiring drug intervention in RYR1-associated myopathy." (PMID 31856875, 2019). "It is important to recognize, however, that there is overlap among subtypes of congenital myopathies, for example, relative sparing of vastus lateralis in CM resulting from variants in RYR1, SEPN1, MYH7, and BIN1." (PMID 30406384, 2018). "Central core disease (CCD) is a congenital myopathy linked to mutations in the ryanodine receptor type 1 (RYR1), the sarcoplasmic reticulum Ca2+ release channel of skeletal muscle." (PMID 29062463, 2017). "Mutations in RYR1 have been associated with congenital myopathies, which form a continuous spectrum of pathological features including a severe variant with onset in utero with fetal akinesia and arthrogryposis." (PMID 26932181, 2016). "Mutations in RYR1 are an important cause/factor of several forms of congenital myopathies, >60 mutations in RyR1 are linked to CCD." (PMID 26793121, 2015). "The recent availability of genetic testing for the entire RYR1 coding sequence has led to a dramatic expansion in the identification of recessive mutations in core myopathies and other congenital myopathies." (PMID 23919265, 2013). "Historically, the overwhelming majority of congenital myopathy patients with mutations in RYR1 had a core myopathy." (PMID 23919265, 2013).
congenital myopathies (continued). "RYR1 mutations are typically associated with core myopathies and are the most common overall cause of congenital myopathy." (PMID 23919265, 2013). "There has been a recent explosion in the identification of new cases of congenital myopathies due to RYR1 mutations, particularly those with recessive inheritance." (PMID 23919265, 2013). "RYR1 (OMIM#180901) mutations in humans lead to congenital myopathy and multi-minicore disease (MmD), which is characterized by amorphous cores in muscle and is similar to those seen in the zebrafish ryr1b mutant." (PMID 19956802, 2009). "In addition to MH, RYR1 mutations have been implicated in a spectrum of congenital myopathies, including central core disease (CCD), multiminicore disease, King-Denborough syndrome, centronuclear myopathy, and congenital fiber-type disproportion." (PMID 41300704, 2025). "Interestingly, one patient was found to carry a pathogenic variant in RYR1, a gene primarily associated with malignant hyperthermia and congenital myopathies." (PMID 41509941, 2025). "Mutations in the RYR1 gene are associated with congenital myopathies." (PMID 39936950, 2025). "Moreover, Rycal drugs were established in several studies as potent stabilizers of dysfunctional RyR1 channels linked to congenital myopathies with symptoms similar to SAMS." (PMID 41392983, 2025). "Besides Lys35‐AC, Lys663‐Ac, and Lys763‐Ac, in the present study, Lys1171‐Ac, Thr1309‐P, Ser1362‐P, Lys1360‐Ac, Lys1410‐Ac, and Lys1733‐Ac were also misregulated in patients with RYR1 mutations and congenital myopathy." (PMID 37602753, 2023). "To understand in greater detail the changes in skeletal muscle function in congenital myopathies caused by recessive RYR1 mutations, we performed an in-depth qualitative and quantitative analysis of protein content and abundance in EDL, soleus and EOMs from WT and dHT mice." (PMID 36862731, 2023). "Indeed, the RYR1 mutation T4980M, associated with a recessive form of congenital myopathy with cores, is located within the RYR1 ATP-binding site." (PMID 35980353, 2022). "However, recent studies have demonstrated a clinical and histopathological continuum between patients with a history of malignant hyperthermia susceptibility and/or exertional rhabdomyolysis and RYR1-related congenital myopathies." (PMID 36751502, 2022). "Mutations in the RYR1 gene have been implicated in a variety of rare congenital myopathies that include, multi-minicore disease (MmD), central core disease (CCD), and to a lesser extent, centronuclear myopathy (CNM), congenital fiber-type disproportion (CFTD), and King Denborough syndrome." (PMID 35698232, 2022). "In order to target these unmet clinical needs we exploited the heterozygous mouse model we created carrying compound heterozygous RyR1 mutations (p.Q1970fsX16 + p.A4329D), for a preclinical study aimed at developing a therapeutic strategy for patients with congenital myopathies." (PMID 35238775, 2022). "Mutations in the RYR1 gene are also a common cause of congenital myopathies." (PMID 35361824, 2022). "In this regard, the direct interaction between the Cav1.1 channel and Ryr1 in the context of the excitation–contraction coupling makes the overlapping phenotypes when one of them is mutated, manifested by episodes of paralysis or congenital myopathy." (PMID 34208776, 2021). "Here we describe a novel and recurrent RYR1 mutation in nine unrelated congenital myopathy families with unspecific findings on the muscle biopsy, and a consistent clinical picture with unusual disease course differing from classical CCD, MmD, CNM, or CFTD cases." (PMID 34535181, 2021). "Indeed, a wide range of clinical phenotypes have been associated with the congenital myopathies resulting from mutations in RYR1, the RyR-encoding gene predominantly expressed in human skeletal muscle." (PMID 31383689, 2019). "RYR1-mutations are the most common cause of congenital myopathies with cores." (PMID 30611313, 2019).
congenital myopathies (continued). "Nevertheless, it is thought that patients with congenital myopathy due to RYR1 mutation may also be at risk of MH." (PMID 29141652, 2017). "Recessive mutations in RYR1 are another cause of congenital myopathies with central nuclei." (PMID 25566070, 2014). "Subsequently RYR1 mutations were described in the context of a variety of histological subtypes of congenital myopathies including central core disease, minicore/centronuclear myopathy with external ophthalmoplegia, centronuclear myopathy and congenital fibre-type disproportion." (PMID 25476234, 2014). "Mutations in RYR1 are the most common cause of congenital myopathies." (PMID 23919265, 2013). "Indeed RYR1 mutations have previously been linked to several congenital myopathies, and also to severe neonatal arthrogryposis." (PMID 22526018, 2012). "Exceptions are the epigenetic silencing of the skeletal-muscle ryanodine-receptor gene (RYR1) that causes congenital myopathies and the MutL Homolog 1 gene (MLH1) that causes increased risk of colorectal or endometrial tumors, which are discussed in the following section." (PMID 22818522, 2012). "Hence, in the present study, we aimed to investigate whether congenital myopathy‐related RYR1 mutations alter the regulation of the most abundant contractile protein, myosin." (PMID 37602753, 2023). "To date, the pathomechanism of disease of recessive RYR1 mutations is not completely understood and for this reason we created a mouse model knocked in for compound heterozygous mutations identified in a severely affected child with RYR1-related congenital myopathy." (PMID 36862731, 2023). "The high expression of HSP70 might thus protect slow twitch muscles from extensive damage linked to the expression of mutant RyR1s, an event which may ultimately account for the fiber type I predominance observed in patients with congenital myopathies linked to RYR1 mutations." (PMID 36862731, 2023). "Therefore, we hypothesize that RyR1 is not only involved in causing congenital myopathies, but implicated in myogenesis and subsequent muscle development." (PMID 35144690, 2022). "Moreover, RYR1 mutations are the most frequent genetic cause of congenital myopathies and it has become increasingly clear that many congenital myopathies are characterized by nonspecific or complex pathological abnormalities rather than a ‘pure' muscle pathology pattern." (PMID 31165076, 2019). "Decreased ryanodine receptor type 1 (RyR1) protein levels lie at the core of recessive RYR1-related myopathies, a class of congenital myopathies." (PMID 40943287, 2025). "In summary, proteomic analysis demonstrates that RyR1 is expressed in intrafusal muscle fibres, along with a large set of other proteins, leading us to next investigate whether Ryr1 mutations affect muscle spindles in a murine model for a RyR1 linked recessive congenital myopathy." (PMID 41091627, 2025). "Scoliosis can develop in congenital myopathies and tends to appear especially early in the more severe ryanodine receptor-1-related myopathy and nemaline myopathy." (PMID 39654599, 2024). "In CCDC78-associated congenital myopathy, muscle cores that show aggregates of CCDC78 also contain aggregates of RyR1." (PMID 38732148, 2024). "Type 1 myofiber predominance is also observed in other triadopathies, including RYR1, DNM2, BIN1 and MTM1-associated congenital myopathies." (PMID 39209426, 2024). "We used skeletal muscle tissues from five patients with RYR1‐related congenital myopathy and compared those with five controls and five patients with RYR1‐related rhabdomyolysis/myalgia." (PMID 37602753, 2023). "We also noted a similarity in the pattern of muscle involvement between RYR1‐related congenital myopathy and the TPM3‐NM group presented here." (PMID 37265148, 2023). "This study also reveals the stoichiometry of major proteins involved in excitation contraction coupling and identifies novel potential pharmacological targets to treat RyR1-related congenital myopathies." (PMID 36862731, 2023).